REN (renin)
Diseases named in the same sentence as REN in open-access papers (continued):
Sharing a sentence is not in itself a finding about the gene and the disease.
Hypertension (continued). "Interestingly, there were no deaths reported in patients with hypertension who were treated with renin-angiotensin-aldosterone system antagonists or amlodipine." (PMID 35011848, 2021). "However, in the present study we have not investigated the involvement of other key mediators of hypertension such as renin-angiotensin-aldosterone system and the endothelin receptors." (PMID 35118089, 2021). "The present study investigates whether doxycycline (DOX, a broad-spectrum tetracycline antibiotic) improves dysbiosis, prevent cardiovascular pathology and attenuate hypertension in deoxycorticosterone acetate (DOCA)-salt rats, a renin-independent model of hypertension." (PMID 34578849, 2021). "The role of AII in maintaining hypertension in this phase is not clear, as both the plasma level of the peptide and plasma renin activity may be near normal." (PMID 33799957, 2021). "However, renin is endogenously expressed in the brain, and increased brain RAS activity is also reported for inducing moderate hypertension; certain experimental evidence also suggests that AGT expression in the brain and circulating AGT regulation is an independent phenomenon." (PMID 34925551, 2021). "ACE participates in the renin-angiotensin-aldosterone system (RAAS), which affects salt retention a protein for water balance and blood vessels; therefore, RAAS controls blood pressure, and drugs that inhibit this enzyme are effective in treating high blood pressure." (PMID 34798807, 2021). "A constant, slight overproduction of aldosterone without renin suppression might explain the mechanism of hypertension in patients with TT genotype." (PMID 32443509, 2020). "We found that the absence of miR-106b prevented the SBP and DBP elevation, increased plasma renin, and stimulation of Ren1c-YFP JG renin production by KODMAC macrophages, suggesting that KODMAC macrophage secretion of miR-106b-5p increases RAS-dependent hypertension in vivo." (PMID 32968066, 2020). "Indeed, evidence is available to suggest that renin–angiotensin–aldosterone system blockers improve coronary microvascular function in patients with hypertension or Syndrome X, though such evidence is lacking for DCM." (PMID 32599970, 2020). "However, in B2-/-, mice hypertension was not exacerbated when induced by mineralocorticoids (renin-independent) or coarctation of the aorta (renin-dependent)." (PMID 33126450, 2020). "The characteristics of dysbiosis are different between systemic renin–angiotensin system (RAS)-dependent hypertension, such as in spontaneous hypertensive rats (SHR), and systemic RAS-independent forms, such as hypertension induced by mineralocorticoid receptor activation." (PMID 33260593, 2020). "Therefore, this research investigated the enzyme inhibition ability of aqueous extracts of nine popular Bangladesh vegetables to determine their potential utility as agents against obesity (PL, α-glucosidase, α-amylase), diabetes (α-glucosidase, α-amylase), and hypertension (ACE, renin)." (PMID 32610462, 2020). "BTTQ demonstrated BP-lowering effects in both normotensive rats and animals with hypertension of different genesis (SHR rat, a high renin model, and Dahl SS rat, a low renin model of salt-induced hypertension) suggesting the pattern of activity independent of primary mechanisms of hypertension." (PMID 33013477, 2020). "The renin‐angiotensin‐aldosterone system (RAAS) plays an important role in the regulation of blood pressure, as evidenced by many genetic forms of human hypertension that map to the RAAS as well by the fact that blockers of this system are frequently used in the treatment of hypertension." (PMID 31397090, 2019). "These similarities suggest that the mechanism of action found in this cohort may be generalizable to other premature infants with idiopathic or unexplained low-renin hypertension, with or without chronic lung disease." (PMID 31028470, 2019).
Hypertension (continued). "In the current study, despite observing similar levels of hypertension and EC-mediated dysfunction between Cx40−/− and Cx40−/−Panx1−/− mice, kidney renin expression and plasma renin activity were enhanced in mice lacking both Cx40 and Panx1 compared with Cx40−/− mice." (PMID 30745457, 2019). "Thus, intrarenal Ang II formation stimulated by the induction of AGT, renin and ACE may contribute to sodium and water retention and high blood pressure." (PMID 31680980, 2019). "The etiology of hypertension differs widely amongst individuals with obesity as a variety of mechanisms directly involved in blood pressure regulation including the sympathetic nervous system (SNS), the renin-angiotensin aldosterone system (RAAS), and fluid balance are altered." (PMID 30364090, 2018). "Similarly, age, BMI and duration of hypertension within slightly different distributions of PA patients with or without DM will determine the activity of renin." (PMID 30332741, 2018). "The classical clinical presentation is severe hypertension in a young patient, with hypokalemia and metabolic alkalosis, in the setting of suppressed renin; however, unlike PA, aldosterone levels are low or undetectable and the syndrome does not improve with MR antagonist therapy." (PMID 29439489, 2018). "However, the median plasma renin value of 34 mU/L in PATHWAY-2 was only three times greater than the median value (11 mU/L) in the 605 patients with untreated hypertension in PATHWAY-1, who had similar blood pressure values on no treatment." (PMID 29655877, 2018). "The approach using renin profile-guided treatment was characterized by equal or better blood pressure control compared with clinical decisions not informed by PRA, and represented the starting approach to physiological phenotyping that laid the foundation for hypertension precision medicine." (PMID 29109301, 2017). "Data were not available to distinguish essential hypertension from secondary hypertension, which is mostly related to hyperaldosteronism, and vitamin D supplementation might closely influence the renin, angiotensin, and aldosterone pathway in the body." (PMID 29135923, 2017). "We hypothesize that CaSR expression and/or functional impairment weakens the inhibition of adenylate cyclase (AC) and increases cAMP formation and renin release, resulting in activation of the RAS, which induces VSMC proliferation and remodeling, thereby promoting the development of hypertension." (PMID 27391973, 2016). "In these patients, who are the majority, suppression of the activity of the renin–angiotensin system by angiotensin-converting enzyme (ACE), or angiotensin II receptor antagonism, is effective in both controlling the BP and reducing the complications of hypertension." (PMID 27774451, 2016). "However, it has still not been fully elucidated whether cardiac tissue levels of prorenin, renin, (P)RR, angiotensin II and angiotensin II AT1 receptor are activated at an early stage of hypertension with a high salt intake." (PMID 25799069, 2015). "Present studies showed that stress-induced hypertension is of complicated pathogenesis which mainly involves the hypothalamus-pituitary-adrenal cortex (HPA) axis, sympathetic nerve-adrenal medulla (SAM) system, renin-angiotensin-aldosterone system (RAS), NO/NOS system, and neuropeptide Y (NPY)." (PMID 26229544, 2015). "Renin, the key enzyme of the renin-angiotensin-aldosterone cascade, plays a crucial role in the regulation of blood pressure, and REN may be a candidate gene for hypertension." (PMID 26090220, 2015). "It would have been important to correlate the angiotensin II levels with renin levels as previous studies have shown majority of blacks to have a low renin hypertension as a result of negative feedback from angiotensin II in a form of apparent minero-corticoid excess." (PMID 26486596, 2015).
Hypertension (continued). "In addition, maternal melatonin therapy elicits longstanding alterations on renal programming, including regulation of the melatonin signaling pathway and upregulation of Agtr1b and Mas1 expression in the renin-angiotensin system (RAS), to protect male offspring against programmed hypertension." (PMID 26696906, 2015). "Natural food-based inhibitors that possess both renin- and ACE-inhibitory effects will usually be preferred as antihypertensive agents because this could provide more effective control of high BP, thus preventing hypertension." (PMID 26715103, 2015). "Hypertension was targeted as a manifestation of ADPKD in the Halt Progression of Polycystic Kidney Disease (HALT-PKD) study, a clinical trial studying the intensive blockade of the renin-angiotensin system with combination ACEIs and angiotensin receptor blockers (ARBs)." (PMID 26275819, 2015). "However, plasma renin activity can be increased by ACEIs or ARB; therefore combination of aliskiren with ACEIs or ARBs has been considered as a preferred option of treatment of hypertension, congestive heart failure, and chronic kidney disease." (PMID 24804145, 2014). "Low renin in itself does not explain the greater occurrence of hypertension or the enhanced vascular contractility reported in this group, and in the presented data, profiling based on age and ancestry was equal or superior to renin in predicting drug responses." (PMID 23721258, 2013). "Therefore, mice lacking vitamin D receptors have elevated production of renin and angiotensin II, leading to hypertension, cardiac hypertrophy and increased water intake." (PMID 23724006, 2013). "It has been reported that suppression of the renin-angiotensin system (RAS) by angiotensin-converting enzyme inhibitors (ACE-Is) and angiotensin II type 1 receptor blockers (ARBs) provides an effective treatment against cardiovascular diseases such as hypertension and cardiac failure." (PMID 23097668, 2012). "In addition to calcineurin inhibition, cyclosporine stimulates PDGF and TGFβ signaling that seems to be involved in mediating renin secretory effects of cyclosporine and it is well established that binding of AngII to AGTR1 leads to vasoconstriction and hypertension." (PMID 21298017, 2011). "In addition to HS diet, a condition where the renin-Ang II system would be downregulated, we also treated mice with Ang II infusion in order to investigate possible interaction with PAR2 on high Ang II acquired hypertension." (PMID 18939990, 2008). "Additionally, the absence of hypertension may indicate a decreased pathophysiological reliance on the renin-angiotensin system, which could explain the potential lower effectiveness of ACE inhibitors in normotensive SRC." (PMID 40084306, 2025). "Collectively, current evidence suggests that while renin inhibitors may serve as an alternative for patients intolerant to ACEi/ARB, they do not demonstrate clear superiority, and their role may be more relevant in specific subgroups such as obesity-related hypertension or advanced microalbuminuria." (PMID 41409925, 2025). "Thus, nonylphenol induced aldosterone increase in female offspring but not adrenocorticotropic hormone, suggesting that nonylphenol may be mediated by the renin‐angiotensin system, leading to hypertension." (PMID 39825581, 2025). "Sympathetic overactivity, the renin-angiotensin-aldosterone system (RAAS), endothelium-derived mediators, erythropoietin-stimulating agents, dialysis-specific factors, and arterial stiffness have also been hypothesized to play a role in intradialytic hypertension." (PMID 38883013, 2024). "Acute Cd exposure may activate the renin–angiotensin system (RAS), increase local release of angiotensin II and elevate activity of COX-2 and NADPH oxidase, and contribute to increased peripheral blood resistance with consequent genesis and maintenance of hypertension." (PMID 37006554, 2023).
Hypertension (continued). "PA is a syndrome characterized by hypertension with (or without) hypokalemia due to pathological changes in the adrenal cortex leading to the autocrine secretion of aldosterone, with high plasma aldosterone concentration and low renin as the main biochemical features." (PMID 35795736, 2022). "Moreover, the results highlighted the idea that MVO could regulate the expression levels of targets, especially for TNF, CHRM1, ACE, IL10, PTGS2, REN, and F2, as well as neuroactive ligand–receptor interaction, the calcium signaling pathway, and PI3K-Akt signaling pathway to treat hypertension." (PMID 35308213, 2022). "Yet, in particular, for the treatment of hypertension, the number of patients with uncontrolled hypertension continues to rise, either due to patient noncompliance or because of the significant renin rises that may, at least partially, overcome the effect of RAS blockade (RAS escape)." (PMID 35904033, 2022). "The mechanisms underlying potential relationships between hypertension and COVID-19 are not known but the key role of the renin-angiotensin-aldosterone system (RAAS)/ACE2 in the pathophysiology of hypertension makes it is possible that any dysregulation of this system may be important." (PMID 34522477, 2021). "Furthermore, volume overload does not always equate to hypertension, because several factors, such as arterial stiffness, high renin states, the osmotic effects of glucose, and the nonosmotic effects of sodium could lead to a complex interplay." (PMID 33459126, 2021). "Similarly, hypertension may result from BRAF and MEK effect on the renin‐angiotensin system." (PMID 33982883, 2021). "Interactions between Wnt/β-catenin pathway and renin-angiotensin system (RAS), which plays an essential role in the maintenance of blood pressure homeostasis, may be an interesting way to better understand the function of Wnt/β-catenin pathway during hypertension." (PMID 34322525, 2021). "However, immune cells have never been shown to directly initiate renin-induced hypertension." (PMID 32968066, 2020). "Lowering intraglomerular pressure using renin–angiotensin system inhibitors may be a useful therapeutic strategy, and SGLT-2 inhibition may have a broader range of renoprotective effects including reductions in body weight, hyperglycaemia as well as intraglomerular hypertension." (PMID 32678323, 2020). "However, there were no observed significant differences in plasma renin during spironolactone, captopril, and tempol treatments, which suggests that the noted hypertension in the present study is more than likely due to the observed differences in intrarenal Ang II." (PMID 33374943, 2020). "We should formally the test the hypothesis that inhibitors of the renin-angiotensin-aldosterone system (RAAS), through effects on glomerular pressure and cardiac remodeling, are preferable to other antihypertensive classes for the treatment of post-donation hypertension." (PMID 29201600, 2017). "We hypothesized that CD renin does not play a role in low Ang-II hypertension." (PMID 27467376, 2016). "IARA combined with measuring the pressure drop over the stenosis would have been an interesting reference method since it has been shown to correlate with the release of renin behind the stenosed kidney, thus a good indicator of whether the stenosis contributes to hypertension or not." (PMID 26459634, 2015). "Genetic NEDD4L variation seems to affect salt sensitivity and P-renin in normotensive subjects, suggesting that genotyping of NEDD4L may be clinically useful in order to identify subjects who benefit from dietary salt restriction in the prevention of hypertension." (PMID 17487281, 2007). "For patients with hypertension and CKD with or without diabetes, renin-angiotensin-aldosterone inhibitors are first line agents." (PMID 40932828, 2025).
Hypertension (continued). "His clinical and biochemical features were hypertension, nonspecific ST and T wave changes on ECG, severe hypokalemia, hypernatremia, metabolic alkalosis, suppressed aldosterone and renin levels, and CK rise without clinical myopathy." (PMID 39807221, 2025). "In addition to the elevated plasma levels of renin, angiotensin II, angiotensin-converting enzyme (ACE), angiotensinogen and aldosterone, renin receptors are also upregulated in patients with obesity compared with lean subjects, all of which may contribute to obesity-mediated hypertension." (PMID 40761303, 2025). "Renal denervation (RDN), as a novel nonpharmacologic intervention for hypertension, is considered to be capable of lowing blood pressure through inhibiting sympathetic nervous system (SNS) and renin-angiotensin-aldosterone system (RAAS) hyperactivity." (PMID 38957519, 2024). "Concerning the first part of the systemic RAS cascade, in a retrospective analysis of patients with hypertension and T2DM, no significant change was observed in plasma renin activity (PRA) with SGLT2 inhibition." (PMID 36875461, 2023). "The adrenergic system and the renin–angiotensin–aldosterone axis may also be involved in the development of treatment-emerged hypertension (TE-HTN), but different findings suggest that this is not the primary mechanism associated with hypertension caused by VEGFR inhibition." (PMID 34830100, 2021). "Some studies showed that GH could increase the levels of renin and aldosterone, but other studies found that without relying on the action of plasma renin, excessive GH could directly stimulate the rise in aldosterone levels, leading to hypertension in patients with acromegaly." (PMID 33869029, 2021). "Pharmacological inhibition of the renin–angiotensin–aldosterone system (RAAS) is, in combination with diuretics, the first-choice treatment for hypertension, although 10–20% of patients do not respond adequately." (PMID 31379575, 2019). "On the other hand, the presence of hypertension in this specific population decreased the possibility of sarcopenia, consistent with the suggestion that not the disease but its treatment with beta-blockers or renin-angiotensin aldosterone inhibitors could prevent muscle wasting." (PMID 29632617, 2018). "Nevertheless, these experimental data provide good evidence to conclude that activation of the renin-Ang II-AT1 cascade is largely responsible for pulmonary fibrosis in RenTgMK mice and the pro-fibrotic effect is independent of high blood pressure." (PMID 26494430, 2015). "Renin–angiotensin–aldosterone system (RAAS) inhibitors were started in 15 patients (27.3%), 7 patients with moderate CTRCD, 7 with mild and 1 without CTRCD due to arterial hypertension." (PMID 40087712, 2025). "However, the expression of renin, a key enzyme of the RAAS pathway which plays an adverse role in hypertension and CKD, and the expression of MasR, have no statistical change between the WT and αMUPA mice following AKI." (PMID 39457635, 2024). "While increased plasma renin activity was reported by several laboratories, and local ACE activity was stimulated in the LV and aorta, serum ACE activity was not increased in l-NAME-induced hypertension." (PMID 29382124, 2018). "For (Hypertension + Vascular Disease), a beta-blocker or calcium channel blocker could treat both conditions and would be preferred to diuretics, ACE, ARB, or renin inhibitors that do not treat atherosclerotic, coronary or cerebrovascular disease." (PMID 29684077, 2018). "The simultaneous inhibition of renin and ACE activities could provide a new alternative way to treat hypertension efficiently without severe negative side effects." (PMID 24603692, 2014). "The aldosterone-to-renin ratio (ARR) is another important marker, however, this factor was detected with a high heterogeneity and is not statistically significant to the uncured postoperative hypertension occurrence (OR = 1.05, 95% CI: 0.87–1.27, P = 0.19, I2 = 98%)." (PMID 40852460, 2025).